CASP1 (caspase 1)
Diseases named in the same sentence as CASP1 in open-access papers (continued):
Sharing a sentence is not in itself a finding about the gene and the disease.
melanoma (continued). "In NLRP3- or caspase-1-knockout macrophages, the ability to promote the migration and invasion of melanoma cells was, similarly, greatly diminished and the metastatic potential of melanoma tumor cells was suppressed." (PMID 33613533, 2020). "However, NLRP3- or caspase-1-knockout macrophages exhibited greatly diminished ability to promote the migration and invasion of melanoma cells." (PMID 31439870, 2019). "The melanoma EV-induced up-regulation of ghrelin, a 28-residue peptide hormone that accelerates the growth of MSCs and has an anti-inflammatory activity, is consistent with the down-regulation of IL-26, IL-17B, caspase-1 and CCL5." (PMID 28129640, 2017). "Besides the enrichment of antiviral interferon response and T-cell-mediated adaptive immunity, GSEA analyses also revealed pronounced induction of genes involved in pyroptosis, including pyroptotic executioner Gsdmd and the inflammatory Casp1 and Casp11 in Mll3−/− and Mll4−/− melanoma cells." (PMID 36323669, 2022). "Inflammasome activation is initiated upon triggering of pattern recognition receptors (Toll-like receptors, NOD-like receptors, and Absent in melanoma like receptors), on the surface of immune cells with the recruitment of caspase-1 by an adaptor apoptosis-associated speck-like protein." (PMID 33014808, 2020). "However, different authors have consistently maintained that EDPs induced the production and/or secretion of IL-1α, IL-1β, and IL-6 in ligamentum flavum cells, synovial cells, and melanoma cell lines; therefore, we can assume that caspase-1 should be activated by EDPs in these cells." (PMID 31691186, 2020). "Thus, we further investigated the mechanisms by which gomesins target melanoma cells using various cell death inhibitors, including necrostatin-1 (necroptosis inhibitor), ferrostatin-1 (ferroptosis inhibitor), VX-765 (caspase 1/4 inhibitor, pyroptosis) and z-VAD FMK (pan-caspase inhibitor)." (PMID 41271646, 2025). "The results showed a significant increase in activated caspase 1 for direct NTP treatment of both A375 (1.3 ± 0.2-fold change, p = 0.0139) and SK-MEL-28 (1.5 ± 0.2-fold change, p = 0.0018) melanoma cells." (PMID 39349444, 2024). "They showed that in melanoma cells, the NALP3 inflammasome is activated by caspase-1 cleavage, leading to continuous caspase activation in metastatic melanoma cells." (PMID 39329914, 2024). "In melanoma, macrophage-derived NLRP3/IL-1β pathway promotes migration and invasion of melanoma cells, which can be blocked through NLRP3 knockout, caspase-1 knockout, or NLRP3 inhibitor, celastrol." (PMID 36932407, 2023). "In melanoma, the NLRP3 inflammasome components, CASP-1, IL-1β, and IL-18, are involved in tumorigenesis and metastasis formation." (PMID 33014808, 2020). "It appears also of great interest that in WM266-4 melanoma cells the SFN/FB combination inhibited inflammasome formation (i.e., NLRP3, cleaved caspase-1 and ASC expression) and IL-1β production significantly more than each single compound." (PMID 32486135, 2020). "For this reason, we evaluated the effect exerted by SFN and FB, administered individually or in combination, on the NLRP3 inflammasome components, as well as on the products of their activation (cleaved caspase-1 and IL-1β) in WM266-4 melanoma cells." (PMID 32486135, 2020). "Additionally, human melanoma cells constitutively express and activate NLRP3, leading to autoinflammation through caspase-1 activity and the production of biologically active IL-1β." (PMID 41017127, 2025). "Their study identified three pyroptosis-related genes—CASP1, CASP4, and PYCARD—that could predict the efficacy of anti-PD-1 immunotherapy in melanoma." (PMID 39329914, 2024). "Thymoquinone decreased the proteolytic cleavage of pro-caspase-1 in B16F10 and A375 melanoma cells." (PMID 35682990, 2022). "Absent in melanoma 2, Asc, and caspase-1 p20 increased after ovalbumin exposure while Nlrp3 did not." (PMID 33707120, 2022).
melanoma (continued). "NLRP1 (NLR family pyrin domain containing 1), confirmed as a proinflammatory protein in melanoma progression, was downregulated significantly by CP, as were the NLRP1-related caspase activation and recruitment domains (CARD) proteins, including caspase-1 and caspase-4." (PMID 30149677, 2018). "S. mutans induced IL-1β secretion via caspase-1 activation, and S. mutans-induced IL-1β secretion required absent in melanoma (AIM2), NLR family pyrin domain-containing 3 (NLRP3) and NLR family CARD domain-containing 4 (NLRC4) inflammasome activation." (PMID 30078841, 2018). "Furthermore, we established a subcutaneous B16-F10 melanoma model for intratumoral BCG treatment and compared wild type mice to TLR2-/-, TLR3-/-, TLR4-/-, TLR7-/-, TLR3/7/9-/-, caspase 1-/-, caspase 11-/-, IL-1R-/-, cGAS-/-, STING-/-, IFNAR-/-, MyD88-/-deficient animals." (PMID 38835781, 2024). "Therefore, therapy targeting ASC, CASP1, and GSDMD in TIDCs may also serve to convert cold melanomas to hot melanomas." (PMID 37046775, 2023). "Furthermore, Treg from melanoma, Treg from TC-1 tumor, Treg from breast tumor, Treg from B16 tumor, Treg from MC38 tumor, and Treg from CT26 tumor upregulated 2, 18, 9, 42, 27, and 9 caspase-1 secretomic genes, and 8, 33, 16, 72, 39, and 11 caspase-4 secretomic genes, respectively." (PMID 34084175, 2021). "Pyroptosis can be triggered by caspase 1 in the canonical pathway, caspase 4/5/11 in the noncanonical pathway, or caspase 3/8 in GSDMC- or GSDME-expressing tumor cells, including melanoma cells." (PMID 38336727, 2024). "As control served the double-stranded DNA mimic dAdT that signals NLRP3 independently via the DNA sensor absent in melanoma 2 (AIM2), still requiring the adapter molecule ASC as well as caspase-1 for the processing of IL-1β." (PMID 29403480, 2017). "In a mouse model of intravenous injection of B16-F10 melanoma cells, researchers found that mice lacking NLRP3 had a significant decrease in lung metastases compared with wild-type mice and that the pathway was independent of caspase-1 and IL-1β." (PMID 31242947, 2019). "However, assembly of a CASP-1 activating inflammasome complex is not restricted to the NLR family, as more recently, the protein absent in melanoma 2 (AIM2) has been shown to contribute to CASP-1 activation and IL-1β release in response to dsDNA." (PMID 23226472, 2012).
myocardial infarction (45 papers, 2010 to 2026). Gross necrosis of the myocardium, as a result of interruption of the blood supply to the area, as in coronary thrombosis. "Caspase-1 deficient mice with myocardial infarction have displayed a significant reduction in mortality and reduced cardiomyocyte pro-apoptosis, decreased MMP-3 activity, and IL-18 production." (PMID 41231039, 2025). "In contrast, caspase-1-deficient mice displayed a significant reduction in mortality after myocardial infarction suggesting a pro-apoptotic role of caspase-1 in the heart." (PMID 38824481, 2024). "In mice, targeted deletion of caspase-1 is associated with reduced postoperative mortality and less left ventricular dilation after myocardial infarction." (PMID 38534442, 2024). "CASP1 genetic variation (G+7/in6A, rs501192) has been associated with susceptibility to myocardial infarction and cardiovascular death risk." (PMID 20184726, 2010). "However, extensive caspase-1 activation and subsequent pyroptosis have also been associated with the severity of several diseases such as myocardial infarction, inflammatory bowel disease, and endotoxic shock." (PMID 30248149, 2018). "In this process, long noncoding RNA myocardial infarction-associated transcripts relieved the depression of caspase-1 by sponging miR-342–3p, thus facilitating caspase-1-dependent pericyte pyroptosis, which may provide novel insight into pericyte loss mechanisms and DR treatment." (PMID 35813208, 2022). "Inhibition of Caspase 1 has also been shown to reduce myocardial infarction size in a rat ischemia–reperfusion injury model." (PMID 38255935, 2024). "Studies with cardiomyocyte-specific overexpression of caspase-1 demonstrated progression of heart failure, while endogenous deletion of caspase-1 was protective during myocardial-infarction-induced heart failure." (PMID 38534442, 2024). "It inhibited NLRP3, IL-1β, and caspase-1 expression in myocardial tissue three days after myocardial infarction." (PMID 36320147, 2022). "After I/R surgery, the size of MI increased, whereas caspase-1 knockout mice showed a better therapeutic effect and reduced the size of myocardial infarction." (PMID 35647057, 2022). "Recent studies have shown that the polymorphisms (BAT1 rs2239527 C/G, NFKBIL1 rs2071592 T/A, LTA rs1800683 G/A, CASP1 rs501192 A/G, and CASP1 rs580253 A/G) are associated with the presence of ACS, myocardial infarction, and CAD." (PMID 35740890, 2022). "Circ-NNT or USP46 knockdown or miR-33a-5p overexpression inhibited the expression of pro-caspase-1, cleaved caspase-1, pro-caspase-11, cleaved caspase-11, IL-1β, and IL-18 in A/R cardiomyocytes and attenuated myocardial infarction in I/R mice." (PMID 34845193, 2021). "The NLRP3 inflammasome, caspase-1, and IL-1β are found to be upregulated in peripheral neutrophils from patients with acute myocardial infarction." (PMID 34776995, 2021). "Following myocardial infarction, caspase-1 activity was increased and the inflammasome was formed in heart tissue; NLRP3 silencing or pharmacologic inhibition prevented inflammasome formation and limited infarct size and cardiac enlargement." (PMID 34776995, 2021). "Inhibition of caspase-1 protected against inflammation and cardiac dysfunction that results from myocardial infarction (MI)." (PMID 30233596, 2018). "To summarise, we were able to demonstrate that the caspase 1 inhibitor, VX-765, was able to reduce myocardial infarction in a model of ischaemia-reperfusion injury." (PMID 29582211, 2018). "The NLRP3 inflammasome is activated in the ischemic heart and the inhibition of the NLRP3-initiated inflammasome during experimental myocardial infarction minimizes the activation of caspase-1 in the heart and improves LV remodeling and function." (PMID 29371912, 2017). "In addition, macrophage-derived EVs enriched in miR-378a-3p have been shown to regulate cell death by blocking activation of the NLRP3/Caspase-1/GSDMD pathways in cardiomyocytes after myocardial infarction." (PMID 40496017, 2025).
myocardial infarction (continued). "Caspase-1, as a key member of the proinflammatory family of caspases, was known for mediating adverse cardiac remodeling in angiotensin II-induced cardiac hypertrophy and surgical myocardial infarction." (PMID 33842546, 2021). "In addition, wild type mice were subjected to myocardial I/R injury and had significant larger myocardial infarct size compared with mice deficient for ASC and caspase-1." (PMID 32648087, 2021). "Inhibition or deletion of caspase 1 improves, e.g., outcome after myocardial infarction." (PMID 32447451, 2020). "The caspase 1 inhibitor, VX-765, was able to reduce myocardial infarction in a model of IR injury." (PMID 29582211, 2018). "NLRP3 inflammasome-activated NLRP3/ASC-dependent inflammatory responses result in the release of significant amounts of caspase-1 and IL-1β, and these innate immune responses play an important role in diabetic cardiomyopathy, myocardial infarction, and MI/R injury." (PMID 29062465, 2017). "It is reported that knockdown of caspase-1 attenuates the right ventricular remodeling induced by pulmonary hypertension in mice, mitigates left ventricular dilation after myocardial infarction in mice, and weakens angiotensin II-induced cardiomyocytes hypertrophy." (PMID 33842546, 2021). "For example, typical signs of pyroptosis such as upregulation of caspase-1 and interleukin 1β (IL-1β) in myocardial infarction (MI) have been reported, suggesting that modulation of pyroptosis may be a viable therapeutic target for alleviating selective cardiovascular diseases such as MI." (PMID 26491223, 2015). "Our recent reports have shown that inhibition of innate immune sensor caspase-1 improves VEGFR signaling, angiogenesis, and neovascularization of progenitor cells after myocardial infarction." (PMID 28335793, 2017). "Conversely, the absence of adapter protein (ASC) and caspase-1 in the inflammasome reduces inflammation and mitigates myocardial infarction progression." (PMID 40672380, 2025). "During myocardial ischemia-reperfusion or non-reperfusion myocardial infarction, the expression of inflammasome components and activation of caspase-1 are upregulated." (PMID 40672380, 2025). "The myocardial infarction area was significantly reduced in rats with myocardial infarction injected with KLF3-AS1 exosome, and the expressions of NLRP3, caspase-1, GSDMD, IL-1β and IL-18 in KLF3-AS1-overexpressed myocardial infarction mice were also significantly decreased." (PMID 37396588, 2023). "Moreover, VX-765 was able to reduce myocardial infarction in a model of IRI, demonstrating that caspase-1 inhibition is an effective method for treating pyroptosis-triggered cardiovascular diseases." (PMID 35673561, 2022). "In another study that the mice underwent permanent CAO, myocardial infarction promoted cardiac contractile dysfunction, and left ventricular myocardial fibrosis, and increased the amount of NLRP3, cleaved caspase-1, cleaved IL-1β, cleaved IL-18 in left ventricular tissue for four weeks." (PMID 36320147, 2022).
Alzheimer disease (43 papers, 2008 to 2026). A progressive, neurodegenerative disease characterized by loss of function and death of nerve cells in several areas of the brain leading to loss of cognitive function such as memory and language. "Primary microglia stimulation in vitro by fibrillar Aβ activates the production of NLRP3 inflammasome, caspase-1, causing the increased secretion of IL-1β in the animal models of Alzheimer’s disease." (PMID 36009120, 2022). "Genetic variations in the inflammatory Caspase-1 gene have been shown associated with cognitive function in elderly individuals and in predisposition to Alzheimer’s disease (AD), but its detailed mechanism before the typical AD onset was still unclear." (PMID 35172755, 2022). "NLRP3 inflammasome-dependent caspase-1 activation is an important pathway related to IL-1β release and has been implicated in the pathophysiology of neurological diseases, including Parkinson’s disease, Alzheimer’s disease, multiple sclerosis, and epilepsy." (PMID 38218765, 2024). "Therefore, NLRP3/ASC/caspase-1 signaling pathways are implicated in the neuroinflammatory effects of Alzheimer’s disease." (PMID 36009120, 2022). "Caspase-1 mutation accelerates the progression of mild cognitive impairment to Alzheimer's disease." (PMID 33509083, 2021). "Previous study has reported that caspase-1/IL-1β is closely associated with Alzheimer's disease." (PMID 33509083, 2021). "Also, knockdown of NLRP1 or caspase-1 reduced neuronal loss in animal models of temporal lobe epilepsy and Alzheimer’s disease." (PMID 31127201, 2020). "The NLRP3 inflammasome is also a key element in Alzheimer’s disease (AD); its activation induces increased synthesis of pro-IL-1β and pro-IL-18 and activates caspase-1." (PMID 38928621, 2024). "In Alzheimer's disease (AD), there is an aberrant activation of inflammasomes, molecular platforms that drive inflammation through caspase-1-mediated proteolytic cleavage of proinflammatory cytokines and gasdermin D (GSDMD), the executor of pyroptosis." (PMID 36895045, 2023). "2-4-Diaminopyrimidine, an important fragment in the inhibition of human caspase-1, is designed to be applied for the treatment of Alzheimer's disease." (PMID 35958114, 2022). "Caspase-1/IL-1β represses membrane transport of GluA1 by inhibiting the interaction between Stargazin in Alzheimer's disease." (PMID 33509083, 2021). "In conclusion, our data demonstrate that caspase-1/IL-1β participates in pathogenesis of Alzheimer's disease." (PMID 33509083, 2021). "Previous study has reported that caspase-1 and its downstream inflammatory factor IL-1β are closely related to Alzheimer's disease." (PMID 33509083, 2021). "Our data demonstrate that caspase-1/IL-1β represses membrane transport of GluA1 by inhibiting the interaction between Stargazin in Alzheimer's disease." (PMID 33509083, 2021). "Our previous study has also found that Ginkgo biloba extract EGb 761 improves the cognitive function of Alzheimer's disease mice by inhibiting the activity of caspase-1." (PMID 33509083, 2021). "Inhibition of caspase-1 improves hippocampal-dependent learning and memory in Alzheimer's disease mice." (PMID 33509083, 2021). "NLRC4 inflammasome induces neuroinflammation and contributes to memory impairment in Alzheimer's disease rats through the activation of caspase-1 and IL-1β." (PMID 33509083, 2021). "TXNIP up-regulation sustains neurodegeneration by activating NLRP3 inflammasome, and enhancing the expression of caspase-1 and IL-1β in the brains of Alzheimer's disease patients." (PMID 33509083, 2021). "In an Alzheimer’s disease mouse model, caspase-1 inhibitor VX-765 dose-dependently reversed cognitive impairment and neuropathology." (PMID 32751738, 2020). "Administration of a reversible small caspase-1 specific inhibitor VX-765 in Alzheimer’s disease model of mice showed improvement of mice clinical behaviors, resulted in decrease in hippocampal and cortical IL-1β levels and prevented amyloid beta deposit." (PMID 31892810, 2019).